CXCR4 (C-X-C motif chemokine receptor 4)
Diseases named in the same sentence as CXCR4 in open-access papers (continued):
Sharing a sentence is not in itself a finding about the gene and the disease.
cancer (continued). "The pSP cells express high levels of CXCR4, which upon activation, may stimulate the cells to move or to undergo ‘epithelial-mesenchymal transition’ (EMT), a process driving cancer progression and malignancy." (PMID 24069258, 2013). "Because TOV-21G cells highly express CXCL12/CXCR4 and CXCL16/CXCR6 axes in spite of a low response to EGF or TNF, these axes may contribute to cancer progression as described by others." (PMID 23800251, 2013). "Although malignant cells from different types of cancers express different chemokine receptor profiles, the chemokine receptor most commonly expressed is CXC chemokine receptor 4 (CXCR4), which binds to the CXC chemokine ligand 12 (CXCL12), also known as stromal cell-derived factor-1 alpha (SDF-1α)." (PMID 22272201, 2012). "All markers identifying cancer stem cells are surface markers such as epithelial cell adhesion molecule (EpCAM), CD44, CD24, CD133 and C-X-C chemokine receptor type 4 (CXCR4) definitely expressed on the normal stem cells at the same time and apparently changing during cancer stem cell development." (PMID 22452810, 2012). "Although these data may suggest divergent functions for CXCR4 and CXCR7 in cancer cells, little is known regarding the frequency of co-expression and therein the mechanism for propagation of CXCL12 signals." (PMID 22472349, 2012). "Coupling of stromal cell derived factor 1 (SDF-1; CXCL12) with its receptor CXCR4, which was previously identified as a major coreceptor for the entry of T-tropic HIV, plays critical roles in inflammation, as well as cancer metastasis." (PMID 22485156, 2012). "In that study, we immunized both Tg and wt mice with the human chemokine receptor CXCR4, which belongs to the G protein-coupled receptor (GPCR) family and plays important roles in the metastatic spread of cancer cells as well as in the entry of HIV in CD4+ cells." (PMID 22558422, 2012). "CXCR4 expression is low or absent in many normal tissues but is expressed by at least 23 different types of tumour cells including cancers of epithelial, mesenchymal, and haemopoietic origin." (PMID 22272201, 2012). "In addition, the CXCR4/CXCL12-axis has been shown to play a pivotal role in trafficking and homing of normal stem cells and metastasis of cancer stem cells to organs that express high levels of CXCL12, such as the lymph nodes, lungs, liver, and bone." (PMID 22485156, 2012). "C-X-C-motif chemokine receptor 4 (CXCR4) and its ligand C-X-C-motif chemokine ligand 12 (CXCL12) have been shown to regulate an organ-specific metastasis by the formation of chemotactic gradients in several cancer." (PMID 22448123, 2012). "In both cancer cell-lines, KU174 demonstrated a dose-dependent reduction in Hsp (Hsc70 and Hsp27), HSF-1 and client proteins (survivin Akt, Her2, nestin, CXCR4 and caspase-3) whereas, a minimal effect was seen on these proteins in normal RPTEC cells (data not shown)." (PMID 22039910, 2011). "CXCR4/CXCL12 axis plays role in cancer cell metastasis and proliferation; the importance of the CXC4/CXCL12 axis may differ in different types of cancer cells, due to their discrete expression." (PMID 22074556, 2011). "A CXCR4-specific small molecule inhibitor, AMD3100 (Plerixafor), was first designed as an HIV-1 entry inhibitor, but is currently administered to mobilize hematopoietic stem cells from the bone marrow and also shows promise as an anti-cancer therapeutic." (PMID 21949786, 2011). "CXCR4 blockage by mRNA silencing or anti-CXCR4 antibodies might restrain the proliferation of CRC cell lines, so that the decreased migration capacity of cancer cells might result from a lower proliferative rate." (PMID 21349176, 2011). "CXCR4 together with its cognate ligand CXCL12 (stromal cell-derived factor-1/SDF-1) is widely expressed in various different cancers, and it is somewhat surprising that its expression did not correlate with patient survival." (PMID 22084725, 2011).
cancer (continued). "Antibodies against CXCR4 have been reported to affect HIV-1 infection and cancer cell migration." (PMID 20049170, 2010). "The chemokine receptors CXCR4 and CCR7 play an important role in cancer invasion and metastasis." (PMID 20181250, 2010). "Due to the involvement of CXCL12/CXCR4 in migration, angiogenesis, and development, it is not surprising that this axis is often exploited by cancer cells for metastasis as well as survival and proliferation." (PMID 20661426, 2010). "In malignant tumors, SDF-1/CXCR4 may provide paracrine signals in promoting malignant progression such as metastasis, invasion and cell proliferation." (PMID 20569497, 2010). "Therefore, the CXCL12 receptors, CXCR4 and CXCR7, should be thought of as a node that connects multiple loops, including the highly important EGF/HER loops, linking cancer (oncogenes) and inflammation." (PMID 20946648, 2010). "Our interest is consequently drawn to its involvement in the induction of CXCR4 expression by H. pylori, a potent inducer of TNF-α, which is known to upregulate a series of cytokines, chemokines, adhesion molecules and growth factors in cancers." (PMID 20699000, 2010). "A tissue with high expression of CXCL12 (for example, liver or bone marrow) may represent a site that preferentially attracts both macrophages and cancer cells, which co-migrate depending on their expression of the CXCL12 receptors CXCR4 and/or CXCR7." (PMID 20946648, 2010). "Furthermore, our data suggest an in vivo role of the chemokine CCL20 in CXCR4 dependent and independent regulation of cancer growth and point to CCR6 and CCL20 as novel therapeutic targets in cancer." (PMID 19340288, 2009). "Because inhibiting CXCR4 or CXCR7 only on 231-control cancer cells did not affect adhesion, these data further emphasize that basal treatment with CXCL12 acts through endothelial CXCR4 to significantly enhance adhesion of circulating cancer cells." (PMID 19484126, 2009). "Co-expression of CXCR4 and CCL20 in the same cancer cells was observed." (PMID 19340288, 2009). "Although the CXCL12/CXCR4 and CXCL12/CXCR7 axes are important factors in cancer cell survival, differences exist between their roles in cancer, and whether they function independently or synergistically should be determined." (PMID 19352387, 2009). "CXCR4 selectively binds the CXC chemokine stromal cell-derived factor 1 (SDF-1, or CXCL12), which has been found to play an important role in tumorigenesis, proliferation, metastasis, and angiogenesis in cancers." (PMID 19002187, 2008). "As expected, all Gli-1 nuclear-positive cancers in the current study expressed CXCR4, COX-2, and VEGF, which was indicative of a cancer progenitor cell-like surface characteristic that might contribute to cancer relapse and treatment failure." (PMID 18475300, 2008). "Given our understanding of CXCR4 signaling, an entirely nuclear localization would not be compatible with a function of this receptor in cancer cell migration and homing." (PMID 19116653, 2008). "Additionally,aberrant activation of signaling pathways within cancer cells, such as thoseinitiated through HER2, can also contribute to elevated CXCR4 expression." (PMID 18779872, 2008). "Importantly, when signalling through CXCR4, CXCL12 stimulates intracellular calcium-flux and chemotaxis in lymphocytes, leukocytes and a range of cancer cells including breast." (PMID 17726466, 2007). "Furthermore, expression of CXCR4, which is known to be upregulated by HER2 overexpression, was found to be slightly increased in HER2-overexpressing cancer cell lines." (PMID 17088902, 2006). "Since cancer cells use the SDF-1/CXCR-4 pathway to spread to bone, we investigated whether ZOL may affect the SDF-1/CXCR-4 chemotaxis mechanism." (PMID 12771933, 2003).
cancer (continued). "Studies have found that interfering with CXCR4 expression or blocking the CXCR4‐CXCL12 axis using small interfering RNA (siRNA) or other inhibitors (i.e., Plerixafor, TN14003, AMD3100) significantly reduces cell viability, invasion, migration, and adhesion of cancer cells in vitro." (PMID 40923371, 2025). "Interestingly, for six genes (KISS1, CXCR4, PSMB9, ABCB1, FGF2, and IL6) found to be up-regulated along with GCS, their overexpression pursuant to platinum-agent treatments in patients promoted resistance to those same agents in cancers." (PMID 40507922, 2025). "Also, CXCL12 acts as a recruiter of CXCR4+ cancer cells, and the physiological expression of CXCL12 in organs such as liver, lungs, and bone marrow promotes metastasis growth in these sites by recruiting CXCR4+ cancer cells." (PMID 40142155, 2025). "Finally, among novel CXCR4 antagonist peptides, LY2510924 and its analog LY25109249, both cyclic peptides developed by Eli Lilly, have been investigated for their potential in treating various CXCR4+ cancers." (PMID 40307933, 2025). "Crosstalk between the CXCL12/CXCR4/ACKR3 axis and the STAT3 signaling pathway has been hypothesized on the basis of findings that both the CXCL12/CXCR4/ACKR3 axis and STAT3 signaling pathway are involved in the progression of several cancers." (PMID 38920657, 2024). "AMD3100, which is an SDF-1α/CXCR4 inhibitor approved by the FDA, has been shown to mitigate radiation-induced skin damage and fibrosis and is used to treat hematopoietic stem cell mobilization for stem cell transplantation in patients with certain types of cancer." (PMID 38256077, 2024). "Chemokine receptor CXCR4 is a highly conserved G-coupled protein receptor (GCPR) first discovered in 1996 as being required for HIV entry into CD4+ T cells and later identified as being expressed in various cell types including hemopoietic stem cells, stromal fibroblast cells, and cancer cells." (PMID 39766093, 2024). "CXCR4 is constitutively expressed in the whole liver tissue and primary hepatocytes, and malignant hepatocytes can express both SDF-1 and CXCR4, suggesting that this pathway can act as an autocrine signal to stimulate cancer cell growth, migration, and invasion." (PMID 38730413, 2024). "A dual MDM2/4 inhibitor, RS3594, and a CXCR4 antagonist, AMD3100, were used to treat human GBM cells and GBM stem-like cells and in addition to inhibiting neurosphere growth and inducing differentiation of GBM cells, AMD3100 and RS3594 demonstrated synergistic effects on cancer stem components." (PMID 39070795, 2024). "For NK cells, one study showed the overexpression of CXCR4, a chemokine receptor commonly found on NK cells, together with a CD19-specific CAR, raising hopes that such double gene-edit may also yield enhanced efficacy of cell therapies in other cancer types." (PMID 36834542, 2023). "However, it is unclear whether high levels of CXCR4 and FAP represent distinct cancer states—especially in solid tumors." (PMID 36672341, 2023). "In addition to these well-studied and clinically relevant genes, novel target structures for theranostic approaches such as C-X-C Motif Chemokine Receptor 4 (CXCR4) and Fibroblast Activation Protein Alpha (FAP) emerged, with a growing spectrum of radioligand therapies in different cancer entities." (PMID 36672341, 2023). "The stiff matrix promotes the expression of C-X-C motif chemokine receptor 4 (CXCR4) and decreases the level of ubiquitin domain-containing protein 1 (UBTD1), which is involved in the proteasome-dependent degradation of YAP, and finally enhances YAP activity in cancer cells." (PMID 35205794, 2022). "In addition, compared with untreated tumors, tumors treated with SGT-53 showed increased mRNA expression of chemokines including Cxcl9, Cxcl10, and Cxcl12, which are associated with increased infiltration of activated T cells in various human cancers via the chemokine receptors CXCR3 and CXCR4." (PMID 36359830, 2022).
cancer (continued). "When considering the significant role of the CXCL12/CXCR4 axis in cell growth, proliferation, and migration, it is clear that the inhibition or blockade of CXCL12/CXCR4 holds promising therapeutic prospects for several diseases but especially for cancer therapy." (PMID 35893797, 2022). "Chemoattractive and adhesion molecules play important roles in the selective homing and retention of cancer cells in the bone marrow vasculature, such as stromal cell-derived factor-1 (SDF-1), a chemokine ligand that binds to CXC chemokine receptors 4 and 7 (CXCR4 and CXCR7)." (PMID 36497192, 2022). "Interestingly, there appears to be a mutual regulation of CXCR4 and NANOG in stem-like cancer cells, which could be mediated by PI3K/Akt/NF-κB and SHH/Gli1 pathways." (PMID 36118530, 2022). "Other studies indicate that the regulatory functions of individual C19MC miRNAs in cancer are related to silencing the expression of factors and signaling pathways related to adhesion, migration, differentiation, growth and angiogenesis (Rap1b, ABCG2, DAPK2, ephrins-EphB2 and EphB4, CXCR4)." (PMID 36430313, 2022). "CXCL12 exerts its function by binding to the seven-transmembrane G-protein-coupled receptor CXCR4 and CXCR7, which were expressed on a great diversity of cell types, including lymphocytes, hematopoietic stem cells, endothelial cells, epithelial cells, stromal fibroblasts, and cancer cells." (PMID 35079936, 2022). "Overall, the emerging scenario suggests that the relative expression levels of CXCR4 and ACKR3 and whether they are expressed in the same or distinct subpopulations of cancer or stromal cells, may have an impact on CXCL12-mediated responses, highlighting a relevant question for future research." (PMID 36233192, 2022). "The absence of T cells in cancer cell nests suggests that the polymeric CXCL12–KRT19 coating of cancer cells may elicit a CXCR4 signal that affects random T cell motility." (PMID 35046049, 2022). "In addition to revealing the promise of CXCR4-targeted 64Cu-CuNCs to be used in TNBC clinical imaging, this study also provided an advantageous method to produce and evaluate the potential of nanoparticles to be applied as cancer theranostics." (PMID 35159648, 2022). "Targeting selectively CXCR4 protein in cancer cells would not be easy." (PMID 33966046, 2021). "Aside from that CXCR4 is largely expressed by epithelial cells and mediates epithelial cell migration via the activation of Rac1, matrix metalloproteinases MMP-14 and MMP-2, and increases the motility of cancer cells through the up-regulation of NF-κB and ERK-dependent pathway." (PMID 34944943, 2021). "Additionally, TPBG modulates cell adhesion, cytoskeletal organization, and mobility by facilitating functional C-X-C chemokine receptor type 4 (CXCR4) expression, leading to C-X-C motif chemokine 12 (CXCL12)-mediated chemotaxis in differentiating ES cells, embryonic fibroblasts, and cancer cells." (PMID 34876581, 2021). "More broadly, both CXCR4 and CCR5 affect a wide array of diseases and homeostatic processes, from cancer to cardiac disease, indicating that effectively targeting co-receptors and manipulating their signaling could be a useful tool in the treatment of a number of diseases." (PMID 34429135, 2021). "Overexpression of multiple signaling impaired CXCR4 constructs suggests that intracellular presence of CXCR4 protein, but neither its surface presence nor CXCL12-CXCR4 mediated signals are essential in modulating DR5 expression and therapy (paclitaxel) resistance in cancer." (PMID 33966046, 2021). "Anti-LAG3 antibodies and CXCR4-targeted therapies are currently being investigated in clinical trials (NCT03470922, NCT02907099, NCT04177810), and our study provides additional rationale to develop these therapeutic strategies, particularly for cancers that arise from or metastasize to the liver." (PMID 33985562, 2021).
cancer (continued). "Then, upon the systemic administration of the reporter protein T22-GFP-H6 and derived cytotoxic constructs, a precise in vivo biodistribution is observed, with the destruction of CXCR4-overexpressing cancer tissues and metastatic foci in the absence of side toxicities." (PMID 34834337, 2021). "Notably, we also discovered that the presence of CXCR4 in cancer cells does not reflect protein expression in the vascular compartment." (PMID 34793563, 2021). "However, inhibitors of MAPK (Mitogen activated protein kinase), EGFR(Epidermal growth factor receptor), TGFβRI (Transforming growth factor receptor 1), and the CXCR4 (C-X-C chemokine receptor) did not inhibit conditioned medium-induced cancer cell scattering." (PMID 32731484, 2020). "The role of Cxcr3 and Cxcr4 signaling axes and their interaction with Ackr3b in cancer progression have not been explored using the zebrafish model in the context of cancer, but it could contribute to clarify the discrepant observations made so far." (PMID 32161595, 2020). "The three scFvs and the anti-CXCR4 antibody as the positive control could bind to the three cancer cell lines (DU145, PC3, and MDA-MB-231), and have no or low binding to 293T and 3T3 as control cells." (PMID 33392074, 2020). "Thus, the NC selectivity in CXCR4+ AML cell uptake, and selective elimination by the payload drug, differs from the molecularly targeted small drugs that inhibit proteins involved in maintaining the cancer stem cell phenotype (e.g. Wnt, Hedgehog NFkB)." (PMID 32295630, 2020). "However, inhibitors of TGFβRI and CXCR4 did not block COM-CM-induced invasion of cancer cells from the spheroids." (PMID 32731484, 2020). "The CXCL12-CXCR4 axis promotes cancer development mainly through two mechanisms: 1) CXCR4-expressing cells are located in CXCL12-expressing organs; and 2) Elevated CXCL12 levels regulate the survival, growth, metastasis and angiogenesis of cancer cells via paracrine signaling." (PMID 32538273, 2020). "They found the motion trajectory of the DCs in the 3D space was driven toward the cancers treated with an epigenetic drug romidepsin and INF-α (RI), but not toward those without treatment, and the RI treatment-driven DC migration was blocked by CXCR4 inhibition." (PMID 32788651, 2020). "We conclude that CXCR4 internalization rate may also contribute to differential cytotoxicity of anti-CXCR4 ADCs to different cell types, including normal versus cancer cells, but it is a cell-specific attribute that is not affected by ADC binding properties." (PMID 30792442, 2019). "We, therefore, hypothesized that CXCR4 antagonism could repress OSCC not by directly targeting cancer cells but by targeting peritumoral stromal cells." (PMID 31336612, 2019). "Expression of CXCR7, but not CXCR4, correlated with the cancer cell response to MCM." (PMID 30993013, 2019). "We recently reported the capacity of triple negative cell lines to induce a cancer stem cell (CSC)-like phenotype and invasion properties into luminal cells, a mechanism mediated by pro-inflammatory cytokines that up-regulated the CXCL12/CXCR4/CXCR7 chemokine signaling axis." (PMID 29928478, 2018). "Thus, CXCR4 has been an attractive therapeutic target in several chronic indications, and various small molecule and peptide inhibitors were generated to target it for the management of HIV-1 infection and cancer." (PMID 29554149, 2018). "Indeed, we have previously demonstrated that CXCL12 either induces HB-EGF shedding in monocytes, which in turn phosphorylates HER1 in bystander cancer cells, and transinhibits HER1 via intracellular G protein-dependent signaling in CXCR4/HER1 double-positive cells." (PMID 29989007, 2018). "Thus, it comes of no surprise that several successful anti-cancer drugs target GPCRs, such as Plerixafor targeting the CXCR4 gene product." (PMID 29861840, 2018).